TNF (tumor necrosis factor)
Diseases named in the same sentence as TNF in open-access papers (continued):
Sharing a sentence is not in itself a finding about the gene and the disease.
infection (continued). "We measured the level of inflammatory cytokines, such as TNF-α and IL-6, in control and ELMO1 shRNA J774 cells after infection with WT Salmonella, with the sifA mutant, or with nonpathogenic bacteria, such as E. coli Nissle-probiotic strain and E. coli DH5α." (PMID 34719317, 2021). "Another study reported that human MoDC infection with HSV-1 strain 17syn+, but not strain KOS, induced increased levels of cytokine expression for IFN-α/β, IL-28, IL-29, TNF-α, and chemokines CCL5 and CXCL10 at 9 hpi, yet at 18 hpi no increase was observed." (PMID 34895058, 2021). "Specifically, in Caco-2 monolayers exposed to 500 ng/mL of 5-HT, expression and protein level of TNF-α, IL-6 and IL-8 were about 3 folds higher in MAP-infected monolayers compared to control cells without infection or 5-HT treatment." (PMID 34799637, 2021). "We also noted that TNF-α+, IFN-γ+, and TNF-α+ IFN-γ+ cells highly infiltrate the lung tissues of old RMs regardless of infection." (PMID 34471088, 2021). "In the DIO mouse, infection with IAV led very early to a significant elevation of systemic pro-inflammatory cytokines, like IL-1β, TNF-α, IFN-γ, and IL-6, in obese mice compared to non-obese mice." (PMID 33810619, 2021). "TNF-α, IL-6, CXCL1, CCL2, and CCL7 levels significantly increased in the sera of klotho WT and KO mice at 1 day post-infection, while the level of IL-12 was not." (PMID 33329595, 2020). "Increased levels of IL-1β, IL-6, and TNFα were detected in sera of PLGA-PEG-treated mice both in the presence and absence of C. albicans-infection (respectively)." (PMID 33091017, 2020). "We observed that S. negevensis effectively blocked TNFα-induced PARP1 cleavage on day 3, but not on day 4 post infection." (PMID 33194844, 2020). "In the absence of Th1 signature cytokines, such as TNF-α, IFN-γ, IL-1β and IL-12, infected mice succumb to infection." (PMID 32517114, 2020). "GO and KEGG analysis of the RNA-seq results revealed overwhelming up-regulation of infection and inflammation-related pathways in the CLP group compared to the sham group, including NF-κB, TNF-α, and cytokine-cytokine receptor signaling (data not shown)." (PMID 33986658, 2020). "In the none-infection group of infants and children, the CD4+IFNγ+TNFα+ double producers were identified to be similar across different ages (left)." (PMID 32849561, 2020). "Consistent with previous findings, LCMV-infected WT mice showed a significant increase of CCL2 on day 3 postinfection and IL-5 on day 7 postinfection, only, while TNF, IL-1β, IL-6, IFN-γ, CCL1 and CCL22 levels did not change following infection." (PMID 32310998, 2020). "Infection with B. abortus at MOI 100 and 1,000 induced IL-6 but not IL-1β nor TNF-α (not shown) secretion by both pre-adipocytes and adipocytes." (PMID 33071987, 2020). "In line with this in our study, Type-1 (IFN-γ, TNF-α, and IL-2)- and Type-17 (IL-17A)- cytokines were significantly decreased in INF individuals when compared to those without Ss infection." (PMID 33042134, 2020). "Explant infection with the Merlin strain resulted in increased expression of MCP-1 and TNF-α; however, the difference was not significant compared with uninfected explants." (PMID 33374185, 2020). "∆M36 infection triggers cell death in all genotypes, indicating IFN-signaling does not contribute to this TNF-dependent pathway." (PMID 33126536, 2020). "Hepatic leukocytes from TgAlbCre-IL10-/- mice produced the highest levels of NO and IFN-γ, while the levels of IL-6, TNF and MIF were increased upon infection but not different between the groups." (PMID 32012211, 2020). "Both cell types exhibited comparable levels of TNF-α and IFN-γ expressing cells, except a higher level of IFN-γ expressing CD8+ non-MAIT cells was seen in the acute phase of infection." (PMID 32572140, 2020).
infection (continued). "Testes infection with JEV showed a differential production of pro-inflammatory cytokines, such as IL-1β, IL-6, IL-8, chemokine RANTES, and TNF-α, as well as an increased presence of NS5 (non-structural protein of the virus), RIG-I, TLR3 and -7." (PMID 32325652, 2020). "The levels of IFN-γ, TNF-α and IL-1β, but not IL-2, at MGAS5005, MGAS315, and MGAS6180 infection sites were higher in SseM1-immunized mice than in control mice." (PMID 32308652, 2020). "Nonsignificant differences in TNF levels persisted between TIGR4 and TIGR4 Δcps infected MDMs 12 and 24 h after infection." (PMID 31551336, 2019). "Immunization and/or infection did not alter cytokines IL-2, IL-4, IL-10, IL-17, IFN-γ, and TNF-α levels; however, IL-6 significantly (p < 0.05) increased, as compared with untreated control." (PMID 31065302, 2019). "Previous study has shown that infection by Vesicular Stomatitis Virus (VSV) is sensitive to IFNβ, but not to TNF, in 2ftGH-derived cells." (PMID 31426476, 2019). "TNF-α was expressed at the same level regardless of live, inactivated, or dead MAH infection; however, the expression of IL-12p70 and IL-10 was confirmed to be induced during the infection of live MAH." (PMID 31440223, 2019). "The flow cytometry data showed that vaccinated (vs. non-vaccinated) mice responded to challenge infection with >8-fold increase in the frequency of Th1 cytokine producing (IFN-γ: 3.9–5.1%, TNF-α: 3.5–5.2%) CD8+T cells (all, *p < 0.05)." (PMID 31293599, 2019). "While we also observed increased frequencies of T-bet+ cDC2As following infection with pathogens known to induce type 1 inflammation (data not shown), we found that IFN-γ, but not TNF-α or TLR signaling, promotes T-bet expression in DC." (PMID 31668803, 2019). "The high levels of the regulatory IL-10 and the lower levels of proinflammatory TNF-α released by the B. abortus-PMN infected Mφs, at the initial stages of the infection, suggested a non-phlogistic phagocytosis mechanism." (PMID 31134082, 2019). "VEGF and IFN-γ also did not have altered expression upon infection, and many samples did not have detectable amounts of IFN-γ, TNF-α, IL-1α, or IL-1β (data not shown)." (PMID 31289185, 2019). "In the absence of infection, addition of IFN-γ and TNF-α trended towards decreasing the amount of incorporated label, IL-13 had no apparent effect, while IL-4 increased the mucin production and transport speed en route exocytosis (p < 0.001)." (PMID 30665337, 2019). "The induction of cytokines (IL6 and TNFα), chemokines (CCL2 and CXCL10), and IFN-I genes in primary C57BL/6 astrocytes following a TMEV-BeAn infection can be mediated by TLR3 but not TLR7 or other MyD88-mediated pathways." (PMID 30669615, 2019). "With respect to innate immune responses we found high induction of TNF and IFN-β in both human and porcine MoDC after infection with JEV, WNV, and USUV, but not with DENV, ZIKV, and Wesselsbron virus." (PMID 30746342, 2019). "While the infection-induced increase of CD8+ T cells producing IFN-γ was not strain related, TNF-α splenic CD8+ T cell secretion potential of SV/129 mice was significantly higher than the one of CD8+ T cells from both BALB/c and C57BL/6 animals (p ≤ 0.0001)." (PMID 30881923, 2019). "The dietary interventions did not affect the production of TNFα when SA11 infection was performed alone, but they did induce an increase in such levels after a double infection when compared with DRI group levels (p < 0.05)." (PMID 29942312, 2018). "Therefore, we hypothesized that TNF was likely not expressed by B or T cells during infection." (PMID 29142134, 2018). "In a previous study investigating the direct infection of human macrophages with Mtb, other stimuli such as LPS, BCG, and individual cytokines including TNF‐α, IL‐1β or IFN‐γ did not drive MMP‐1 production." (PMID 29210073, 2018).
infection (continued). "The expression of TNF was increased due to infection in the WT group, only in pregnant females (P < 0.01), whereas in the MIF-/- group, infection induced increased TNF expression in both pregnant and non-pregnant females (P < 0.05)." (PMID 29867817, 2018). "By contrast, production of TNF-α, IL-6, and IL-10 did not change in G2A KO BMDMs with or without LPC treatment during H37Ra infection." (PMID 29755479, 2018). "On a systemic level (plasma) 12 h post-infection IL-6, IL-10, and MCP-1 was higher in TFPI-2−/− mice and no significant changes were observed in INF-γ, TNFα, and IL-12p70, whereas in BALF fluid, IL-10, and MCP-1 was higher in TFPI-2−/− mice." (PMID 30254643, 2018). "Although LPC treatment increased production of the pro-inflammatory cytokines TNF-α and IL-6 in a dose-dependent manner in Mtb-infected macrophages (data not shown), the production of TNF-α and IL-6 was decreased in LPC-treated WT BMDMs after H37Ra infection." (PMID 29755479, 2018). "Protection is dependent on MR1, IFN-γ and GM-CSF, but not IL-17A, TNF or perforin, and enhanced protection is detected earlier after infection of mice antigen-primed to boost MAIT cell numbers before infection." (PMID 30135490, 2018). "The combined action of TNFα and IFNγ 14-folded the NO2- generation in the non-infected in vitro mucosal membranes (p<0.001), and infection further increased it (p<0.001)." (PMID 30252907, 2018). "A comparative analysis of the secreted cytokines profile upon monocytes and neutrophils depletion suggested a protective role against infection for IL-2, IFN-γ, and TNF-α from macrophages, while IL-10 secretion seems not to be affected." (PMID 30197647, 2018). "Together, these results suggest that Tc infection induces a significant increase in PPAR-α expression and TNF-α and IL-6 production in Mφs; however, PPAR-α is not the prime regulator of the pro-inflammatory cytokine response in infected Mφs." (PMID 29503646, 2018). "The presence of TNF was slightly lower in the AAS group, especially at week 3 post-infection (difference not statistically significant)." (PMID 29740435, 2018). "When activated by a second round of infection, the TEM cells release pro-inflammatory cytokines, most notably TNF-α, TGF-β, and IL-2." (PMID 29783736, 2018). "In this study, we found that absence of TNF reduced the number of CD169+ cells; inhibited IFN-I production; and, consequently, led to a severe disease outcome during infection with VSV." (PMID 29142134, 2018). "Progressive mitochondrial dysfunction was mimicked in the absence of infection by treatment with TNF-α or AA, suggesting that it is controlled by the TNF-α/cPLA2/AA pathway." (PMID 28634388, 2017). "Even a higher concentration of conidia (multiplicity of infection of conidia and macrophages, MOI 5:1) was not sufficient to raise the levels of TNF-α and IL-12." (PMID 28355277, 2017). "Skin pigmentation was seen in most of the infection sites, with the exception of three mice receiving CTLA4 Ig and one receiving anti-TNF that never developed skin necrosis." (PMID 28264025, 2017). "Whereas the combination of TNF-α and infection with E. coli did not increase apoptotic rates in PBMO, it in contrast significantly enhanced the CBMO apoptosis rates, compared to infection alone (p < 0.05)." (PMID 28793310, 2017). "Groups f/mf, m/mf, mf/mf and -/mf displayed comparable levels of TNF-α and IFN-γ that were higher than those in the naive controls, indicating that a second infection does not influence TH1-response." (PMID 28542175, 2017). "IL-17 plays a crucial role in resistance to infection and absence of this cytokine in mice has increased T. cruzi in the liver, heart and kidney and decreased inflammatory cytokines such as IFN-γ, TNF-α and IL-6." (PMID 29255475, 2017). "By contrast, TNF KO mice did not resist pleural BCG infection and died at 7–9 weeks after infection." (PMID 28890718, 2017).
infection (continued). "It was observed that rTgHSP70 immunization did not alter the production of IL-2, IL-4, IL-6, IL-10, IL-17a, IFN-γ, nor TNF, although infection with T. gondii promotes the production of inflammatory cytokines IL-6, IFN-γ, and TNF in all groups of mice." (PMID 28487847, 2017). "This study shows that gerbils did not respond early to PbA infection as revealed by expressions of inflammatory cytokines such as IFN-γ and TNF." (PMID 29034874, 2017). "As observed for all other cells, infection of bovine CD14+ cells with wt BRSV did not induce phosphorylation of p65 and in fact blocked TNF-α-mediated phosphorylation of p65." (PMID 28714847, 2017). "At 72 h upon i.p. infection with Lb, macrophages from both B6 and BALB/c mice expressed an inflammatory phenotype, by producing TNF-α, G-CSF, and NO, but not IL-10 in Lb-stimulated cultures." (PMID 29204144, 2017). "In the infection with O. tsutsugamushi TLR2, but not TLR4, is required for the release of TNFα and IL-6 by dendritic cells (DCs) upon pathogen contact." (PMID 28770333, 2017). "Infection of THP-1 cells with wt BRSV did not induce phosphorylation of p65 and wt rBRSV blocked TNF-α-mediated phosphorylation of p65." (PMID 28714847, 2017). "After 9 days of infection, neither Tha nor Th4M induce the expression of IFNß, CXCL2 or TNF in BALB/c." (PMID 29084252, 2017). "We also found that when LAM-exposed MDM were activated with LPS, they produced less TNF, and the transcription factor proteinase-activated receptor-2 (PAR2), which is involved in host immune responses to infection, was not induced." (PMID 29230224, 2017). "Early after challenge with virulent M. bovis [3 weeks post-infection (WPI)], non-vaccinates had greater (P < 0.05) IFN-γ/TNF-α responses to PPD, Ag85A/TB10.4, and ESAT-6:CFP10 by Tcm cells than did vaccinated animals." (PMID 27799930, 2016). "We used a fixed amount of anti-TNF-α and anti-HMGB-1 agent for our treatment, which fails to compromise an elevated level of TNF-α and HMGB-1 at a later stage of infection." (PMID 27556404, 2016). "Other cytokines and chemokines, such as IL-1β, IL-10, IL-17, TNF-α, IFN-γ, RANTES, and EOTAXIN, were also upregulated in the serum upon infection, but to a relatively lesser extent (data not shown)." (PMID 27756321, 2016). "The release of IFNα2 and TNFα did not mimic virus propagation kinetics as was seen in human MDM, but was a staged response with TNFα appearing early in the infection and IFNα2 increasing at 3–5 dpi." (PMID 27191161, 2016). "Early upon infection, vaccinates exhibited higher numbers of antigen-specific IFN-γ/TNF-α/IL-2 Tcm cells than did non-vaccinates, and such dissimilar responses between vaccinates and non-vaccinates early after challenge is associated with disease outcome." (PMID 27799930, 2016). "Early after challenge (3 weeks post-infection), non-vaccinates had greater antigen-specific interferon-γ (IFN-γ)/tumor necrosis factor-α (TNF-α) and lesser IFN-γ/TNF-α/IL-2 responses by Tcm cells than did vaccinated animals." (PMID 27799930, 2016). "Regarding TNF-α, EPEC did not induce TNF-α secretion at any time tested while EHEC only induced a modest response at 4 h of infection." (PMID 27774437, 2016). "Although loss of type I IFN signaling decreased Tnf expression during in vivo infection in the absence of IFN-γR, TNF production in response to M. tuberculosis infection in vitro was not significantly different between WT and Ifnar−/− macrophages." (PMID 27849167, 2016). "In the present study, however, neutrophil accumulation and TNF-α, IL-1β, IL-17A and MIP-2 synthesis in the lungs after infection with S. pneumoniae were not significantly different between WT and Dectin-2KO mice." (PMID 26727976, 2016). "We found that macrophages from gp91phox−/− and WT mice produced similar levels of IL-6, TNF-α, IL-17A and CXCL-1, MCP-1 and IL-10, regardless of infection with L. amazonensis." (PMID 27056545, 2016).
infection (continued). "As expected, in condition allowing viral integration (conditions of infection by HIV-1 env−gfp+ WT virus in the absence of RAL), treatments stimulating the NF-κB pathway (i.e. TNF-α, PRO and PHA) promoted HIV-1 expression." (PMID 27167871, 2016). "In O. tsutsugamushi infection, 2-APB suppressed expression of TNF-α, whereas in LPS infection, 2-APB increased the TNF-α level; yet, for both pathogens, TNF-α was not released to the outside due to 2-APB mitigation of SOCE." (PMID 27472555, 2016). "At 4 and 9 weeks post-challenge, increased levels of triple-positive CD4+ T cells (co-expressing IFN-γ, TNF-α and IL-2), but not CD8+ T cells, were observed in the spleens and lungs of the Rv3628-immunized group compared with the infection control group." (PMID 27097115, 2016). "The expression of endocan is up-regulated in response to TNF-α or IL1-β in vitro, although the precise mechanism of endocan expression in infection has not been elucidated." (PMID 25894539, 2015). "Infection with D39 (1–100 MOI) did not induce significant (p>0.05) NF-κB activation, compared to activation with TNFα or Nm-OM (p<0.05)." (PMID 26566142, 2015). "While TNFα treatment of M-CSF-treated peritoneal macrophages did not inhibit EBOV GP/rVSV replication, the addition of IFNγ prevented infection in either BALB/c or C57BL/6 peritoneal macrophages." (PMID 26562011, 2015). "Alteration of IL-8 and TNF-α expression was not completely compromised, in contrast a substantial levelq of IL-8 and TNF-α mRNAs remained detected over 12 h of infection." (PMID 26241037, 2015). "Secretion of IL-10 and TNF-α induced by AO3 and AR39 infection was also the same (data not shown), while IL-6 secretion was higher for AR39 but only for one MOI and only at 35 °C." (PMID 26494400, 2015). "Prior to infection (0 h), no expression of IE1–72 was identified, the expression levels of TLR2 and TNF-α were low, and the expression levels of TLR4 and NF-κB were high." (PMID 25435993, 2015). "Similar to TNF-alpha expression by CD4+ T cells after 72 hours, infection with either strain did not induce an increase expression of granzyme A." (PMID 26147698, 2015). "The infection is normally cleared within ∼50–60 d, in a manner that depends on IFN-γ but appears independent of TNF." (PMID 26002976, 2015). "Colonic TNF-α protein and IFN-γ mRNA expression levels increased almost two-fold 7 days following parental, but not ∆htrA infection (p < 0.01 and p < 0.05, respectively) further underlining the role of HtrA in aggravating C. jeuni mediated inflammation." (PMID 24883112, 2014). "Pre-infection with Y. pseudotuberculosis blocked SFL-induced caspase 3 activity but not that by STS, sulfasalazine or TNFα and CHX." (PMID 24498214, 2014). "In a human infection model, carriage of S. pneumoniae increased the prevalence of CD4+IL-17A+TNF+IFN-γ+ Th cells in lungs and blood, as compared to non-carriers." (PMID 25119879, 2014). "We also found evidence that the attenuation of infection was mediated by protective mechanisms induced by the anti-viral, pro-inflammatory cytokines IFN-α and TNF-α, but not caspase-1." (PMID 25061945, 2014). "However, after a four day recovery, the DMSO and TNFα treated samples were largely indistinguishable in terms of the sizes of the ‘red’ and ‘yellow’ populations, suggesting that TNFα treatment at day four post-infection had not permanently altered the proportion of non-productively infected cells." (PMID 24502247, 2014). "Females and castrated males expressed significant higher TNF-α, IFN γ, IL12, iNOS and IL17 than non-castrated males during the first month of infection." (PMID 24722144, 2014). "However, the proinflammatory cytokines TNF-α and IL-1β had no decreasing effects on virus replication, suggesting that these cytokines contribute to innate immunity by other mechanisms, like inducing inflammation on the site of infection and recruiting other inflammatory cells to infected tissues." (PMID 24804732, 2014).